CEP164 (centrosomal protein 164)
Description:
Plays a role in microtubule organization and/or maintenance for the formation of primary cilia (PC), a microtubule-based structure that protrudes from the surface of epithelial cells. Plays a critical role in G2/M checkpoint and nuclear divisions. A key player in the DNA damage-activated ATR/ATM signaling cascade since it is required for the proper phosphorylation of H2AX, RPA, CHEK2 and CHEK1. Plays a critical role in chromosome segregation, acting as a mediator required for the maintenance of genomic stability through modulation of MDC1, RPA and CHEK1.
Synonyms: KIAA1052; NPHP15
Tractability: PROTAC: ubiquitination databases record sites on it.
Gene: Protein-coding gene on chromosome 11 (117,314,557 to 117,413,605, forward strand). Ensembl gene ENSG00000110274.
Subcellular location: Cytoplasm, cytoskeleton, microtubule organizing center, centrosome, centriole; Nucleus
Subcellular location (Human Protein Atlas): Centrosome; Primary cilium transition zone; Principal piece; Equatorial segment; Nucleoplasm; Vesicles
Pathways (Reactome):
Cell Cycle: AURKA Activation by TPX2; Loss of Nlp from mitotic centrosomes; Loss of proteins required for interphase microtubule organization from the centrosome; Recruitment of NuMA to mitotic centrosomes; Recruitment of mitotic centrosome proteins and complexes; Regulation of PLK1 Activity at G2/M Transition
Organelle biogenesis and maintenance: Anchoring of the basal body to the plasma membrane
Gene Ontology:
Molecular function: protein binding
Biological process: cilium assembly
Cellular component: centriole; centrosome; ciliary transition fiber; extracellular region; nucleoplasm; cytosol; nucleus
Genetic constraint (gnomAD): Loss-of-function variants: 152 observed, 172.32 expected, observed/expected ratio (o/e) 0.88, 90% interval 0.77 to 1.01. The upper end of that interval is the gene's LOEUF score, 1.01, which puts it in group 4 of 6, group 1 being the genes least tolerant of losing a copy. Missense variants: 1,664 observed, 1,782.2 expected, observed/expected ratio (o/e) 0.93, 90% interval 0.9 to 0.97. Synonymous variants: 645 observed, 691.63 expected, observed/expected ratio (o/e) 0.93, 90% interval 0.87 to 1.
Gene-disease validity (ClinGen):
ClinGen rates the evidence that CEP164 causes each of these diseases.
CEP164-related ciliopathy (autosomal recessive): Definitive. Any ciliopathy caused by variants in the CEP164 gene.
Homologues: Orthologues: chimpanzee CEP164 (99% identical), macaque CEP164 (85% identical), dog CEP164 (74% identical), rabbit CEP164 (72% identical), pig CEP164 (69% identical), mouse Cep164 (67% identical), rat Cep164 (66% identical), guinea pig CEP164 (60% identical), tropical clawed frog cep164 (34% identical), Drosophila melanogaster GCC185 (7% identical). Paralogues in human: NUMA1 (15% identical), GCC2 (13% identical), GOLGA3 (13% identical).